RN7SKP13 (RN7SK pseudogene 13)
Gene: Miscellaneous RNA gene on chromosome 4 (181,834,865 to 181,835,108, reverse strand). Ensembl gene ENSG00000251742.
Homologues: Orthologues: chimpanzee 7SK (85% identical). Paralogues in human: RN7SKP217 (61% identical), RN7SKP44 (61% identical), RN7SKP204 (60% identical), RN7SKP50 (60% identical), RN7SKP250 (59% identical), RN7SKP30 (59% identical), RN7SKP77 (59% identical), RN7SKP186 (59% identical), RN7SKP240 (59% identical), RN7SKP15 (59% identical), RN7SKP176 (59% identical), RN7SKP189 (59% identical), and 283 more.